MYC (MYC proto-oncogene, bHLH transcription factor)
Diseases named in the same sentence as MYC in open-access papers (continued):
Sharing a sentence is not in itself a finding about the gene and the disease.
cholesteatoma (continued). "c-MYC expression was significantly higher in both cholesteatoma groups compared to that of atheroma specimens and to controls (cholesteatoma-atheroma comparison: Pchildren = 0.001 and Padults = 0.002; cholesteatoma-control comparison: Pchildren = 0.0145 and Padults = 0.0312)." (PMID 24683550, 2014). "The significant difference in c-MYC gene expression level in cholesteatoma compared to that of atheroma implies a more prominent hyperproliferative phenotype which may explain the clinical behavior typical of cholesteatoma." (PMID 24683550, 2014). "Our finding that c-MYC expression was higher in the cholesteatoma matrix of children could explain the higher recurrence rate in this group compared to that of the adult group." (PMID 24683550, 2014). "It enables to detect and quantify the extent of abnormal c-MYC gene expression that could be present in cholesteatoma." (PMID 24683550, 2014). "The characteristic alterations present in cholesteatoma indicate abnormal c-MYC gene expression and could warrant for the precise determination of the c-MYC gene expression level in cholesteatoma samples." (PMID 24683550, 2014). "The increased c-MYC expression level in the cholesteatoma matrix compared to that of the atheroma matrix might explain the more aggressive behavior of cholesteatoma that results in clinical complications and it also explains its more intensive proliferation." (PMID 24683550, 2014). "The highest c-MYC expression level was found in children with recurrent cholesteatoma." (PMID 24683550, 2014). "The elevated c-MYC level reported in this study might have a dual role; it promotes cell proliferation and can sustain the chronic inflammation process in cholesteatoma." (PMID 24683550, 2014). "Since c-MYC is evolutionary stably expressed in several different cell-lines, and participates in a range of cellular functions such as proliferation and differentiation, it was likely to be seen in the middle ear mucosa in healthy and cholesteatoma diseased ears." (PMID 32915926, 2020). "Validation of reference genes using c-MYC expression confirmed the suitability of ACTB and GAPDH as reference genes and showed an upregulation of c-MYC in middle ear mucosa during cholesteatoma." (PMID 32915926, 2020). "Previous studies have found aneuploidy of chromosome 8, copy number variation of c-MYC gene, and the presence of elevated level c-MYC protein in cholesteatoma." (PMID 24683550, 2014). "Using this method, we aimed to investigate whether the middle ear mucosa in ears with cholesteatoma has altered gene expression in relation to its control tissue by the examination of TLR2, TLR4 and c-MYC." (PMID 32915926, 2020). "Our results showed a significantly elevated expression of c-MYC gene in cholesteatoma, compared to that of atheroma and normal skin samples.The expression level of c-MYC gene in pediatric cholesteatoma was higher than in adults." (PMID 24683550, 2014). "The difference in c-MYC expression was not significant between the two cholesteatoma groups (P = 0.195)." (PMID 24683550, 2014). "The highest c-MYC expression was found in children with recurrent cholesteatoma; however, the difference was not significant in any of the pairwise comparisons." (PMID 24683550, 2014).
chronic kidney disease (4 papers, 2020 to 2025). Impairment of the renal function secondary to chronic kidney damage persisting for three or more months. "MYC is a well-characterized factor contributing to cystogenesis, and ADM is a biomarker for chronic kidney disease." (PMID 31979107, 2020).
endometrioid adenocarcinoma (4 papers, 2021 to 2025). An adenocarcinoma characterized by the presence of malignant glandular epithelial cells resembling endometrial cells. "In addition, the expression of MYC and CXCR2 in the tumor related to non-endometrioid adenocarcinoma and reduced the risk of recurrence, respectively, and higher NR5A2 expression in tumor-adjacent tissue increased the risk of death." (PMID 36140779, 2022). "In patients with cancer-free tumor-adjacent tissue, higher MYC expression in the tumor increased the probability that tumor type was not endometrioid adenocarcinoma (OR 5.079, 95% CI [1.274–20.244], p = 0.021)." (PMID 36140779, 2022).
fibrosis (4 papers, 2016 to 2025). the formation of excess fibrous connective tissue in an organ or tissue in a reparative or reactive process. "For instance, MYC, with the highest degree value, plays a crucial role in hepatocyte apoptosis, liver fibrosis, and HCC in the MASLD mouse model." (PMID 40520339, 2025). "Some proteins of these genes have already been associated with pathophysiological processes in the kidney: in tubulointerstitial fibrosis (c-MYC, PTEN, STAT3, HIF-1α, PT53); podocyte injury (EGFR, PT53, CTNNB1, CREB1); epithelial-mesenchymal transition (PTEN); and glomerulosclerosis (DICER1, IL1β)." (PMID 37035314, 2023).
influenza (4 papers, 2015 to 2021). An acute viral infection of the respiratory tract, occurring in isolated cases, in epidemics, or in pandemics; it is caused by serologically different strains of viruses (influenzaviruses) designated A, B, and C, has a 3-day incubation period, and usually lasts for 3 to 10 days. "We observed that older adults who developed immune responses to influenza vaccine had increased aging signature genes including those targeted by MYC, BATF, and/or SATB1 compared to older adults who were vaccine nonresponders." (PMID 31044512, 2019). "We cloned the coding region of hGATAD1 tagged with the human influenza haematogglutinin epitope (HA) or human ZNF573-tagged with both MYC and FLAG epitopes into a lentivirus vector (LV) that expressed GFP." (PMID 26671628, 2015). "We quantified the expression of four human mRNAs, two mRNAs that are significantly reduced during influenza infection (CHML and KIF18A, cluster 1) and two mRNAs that were less affected by infection (MYC and CDKN1B, cluster 3)." (PMID 27525483, 2016).
leukocytosis (4 papers, 2012 to 2025). "Mice transplanted with MYC/BCL-XL had a pronounced leukocytosis compared to Mock/Mock transplanted mice." (PMID 22393362, 2012).
lymphopenia (4 papers, 2016 to 2023). Reduction in the number of lymphocytes. "In all Vk*MYC mouse models, increasing tumour burden was associated with a progressive B lymphopenia; however, alterations in the T cell profile differed." (PMID 27599546, 2016). "In fact, in both Asciz or Dynll1 mutant mice, there was a trend towards a modest rescue of the B-1a lymphopenia by Eμ-Myc, possibly reflecting increased MYC-driven self-renewal of the B-1a cell pool." (PMID 28922373, 2017). "Together, these data indicate that deregulated c-MYC expression in λ-MYC mice leads to peripheral B cell lymphopenia resulting from defects in B cell generation at two different levels: impaired BM differentiation and aberrant migration of B cell precursors from the BM." (PMID 37809061, 2023).
lymphoproliferative disorders (4 papers, 2012 to 2023). "Further understanding of the interplay between MYC and ferroptosis may improve the treatment of MYC-driven lymphoproliferative disorders." (PMID 38007476, 2023).
Merkel cell carcinoma (4 papers, 2019 to 2025). "Virus-positive Merkel cell carcinoma (MCC) serves as an ideal model to explore PRMT5’s role in alternative splicing regulation, as it is driven by the MYC paralog MYCL." (PMID 40846633, 2025).
myocardial ischemia (4 papers, 2011 to 2023). A disorder of cardiac function caused by insufficient blood flow to the muscle tissue of the heart. "Unexpectedly, exosomes from MYC-transformed MSCs were able to reduce relative infarct size in a mouse model of myocardial ischemia/reperfusion injury indicating that the capacity for producing therapeutic exosomes was preserved." (PMID 21513579, 2011).
papilloma (4 papers, 2010 to 2020). A benign epithelial neoplasm that projects above the surrounding epithelial surface and consists of villous or arborescent outgrowths of fibrovascular stroma. "Immunohistochemical characterization of papillomas revealed strong activation of Ras-dependent phospho-ERK consistent with previous studies as well as robust MYC expression associated with skin neoplastic transformation." (PMID 21042537, 2010). "Expression of ectopic MYCWT or MYCT58A in papillomas resulted in decreased expression of endogenous cMyc mRNA, consistent with other models where ectopic MYC has been shown to autoregulate and suppress its own promoter." (PMID 32895364, 2020).
Parkinson’s (4 papers, 2022 to 2025). "Interestingly, significant signatures included KEGG disease pathways such as Alzheimer’s and Parkinson’s as well as the previously noted HALLMARK Unfolded Protein Response and MYC Target signatures." (PMID 36271092, 2022).
pheochromocytoma (4 papers, 2017 to 2024). "MAX is the associated factor X of MYC (MAX and MYC together form a protein complex that is a transcriptional activator) and is associated with pheochromocytoma." (PMID 35428183, 2022). "Notably, although the interaction of MAX and MYC is considered to be activating, mutations in the MAX gene resulting in pheochromocytomas involve loss of function of this protein, whereas the activity of MYC in tumors is elevated." (PMID 28187001, 2017). "Furthermore, genes encoding the MYC proteins and cyclin D1, which are associated with cell transformation in pseudohypoxic renal cancer, exhibit elevated expression in paragangliomas/pheochromocytomas with mutations in HIF2A." (PMID 28187001, 2017).
primitive neuroectodermal tumor (4 papers, 2012 to 2025). A malignant neoplasm that originates in the neuroectoderm. "Furthermore, stabilization of HIF1α and up-regulation of MYC have been revealed in central nervous system primitive neuroectodermal tumors (CNS-PNET) animal model." (PMID 33572152, 2021). "Interestingly, MYCN showed high-level focal amplifications in a subset of GBM samples, and MYC or MYCN is found to be amplified in almost half of brain cancers that have combined features of malignant glioma and primitive neuroectodermal tumors (MG-PNET)." (PMID 22348395, 2012).
soft tissue sarcoma (4 papers, 2018 to 2025). A malignant neoplasm arising from muscle tissue, adipose tissue, blood vessels, fibrous tissue, or other supportive tissues excluding the bones. "MYC CNA in high grade adult soft tissue sarcomas have been reported as rare events (7 of 207, 3.4%)." (PMID 29765529, 2018). "However, no studies to date have investigated the relationship between c-MYC expression and doxorubicin resistance in soft tissue sarcomas." (PMID 41438985, 2025).
thymic carcinoma (4 papers, 2017 to 2023). Thymic carcinoma (TC) is a type of thymic epithelial neoplasm characterized by a high malignant potential. "Bioinformatic analysis of TGCA data showed a positive correlation between METTL3 and c-MYC mRNA levels in Thymoma and Thymic carcinoma samples." (PMID 34530916, 2021). "The focal MYC amplification was remarkable in thymic adenocarcinoma while thymic carcinomas showed broad chr8q amplifications." (PMID 28506304, 2017). "Consistent with these evidences, we validated c-MYC as target of METTL3-dependent methylation also in Thymic carcinoma and showed the requirement of METTL3 for an efficient c-MYC expression in TC1889 cells, suggesting that METTL3 might enhance cell proliferation by promoting c-MYC translation." (PMID 34530916, 2021).
tongue cancer (4 papers, 2011 to 2022). A malignant neoplasm affecting the tongue. "L-685,458 was also shown to down-regulate c-MYC expression as well as NF-κB and NOTCH pathways in tongue carcinoma cells." (PMID 32748879, 2020).
acinar adenocarcinoma (3 papers, 2016 to 2023). "Induction of MYC in acinar cells using an elastase 1 c-Myc (Ela-1-MYC) transgene typically gives rise to acinar carcinomas, as well as tumors that display both acinar-like and duct-like features." (PMID 37452870, 2023).
adenoid cystic carcinoma (3 papers, 2024 to 2026). A malignant tumor arising from the epithelial cells. "MYBL1 and MYC genes are linked via the pathway associated with adenoid cystic carcinoma." (PMID 38473786, 2024).
adenosquamous carcinoma (3 papers, 2017 to 2022). A carcinoma composed of malignant glandular cells and malignant squamous cells. "Cells transformed by both AR/AKT/ERG and c‐MYC/sgPTEN generated heterogeneous tumors including adenocarcinoma and adenosquamous carcinoma, consistent with a recent report." (PMID 28297567, 2017).
Anxiety (3 papers, 2023 to 2024). Intense feelings of nervousness, tension, or panic often arise in response to interpersonal stresses. "MYC accelerates anxiety by promoting the expression of 5HT2AR/5HT1AR." (PMID 37273529, 2023). "However, a potential mechanism by which E2F5 and/or c-MYC regulate anxiety-related disorders remain unknown, and the role of E2F5/c-MYC interaction in regulating downstream genes involved in anxiety has not been addressed so far." (PMID 36979479, 2023).
atrophic gastritis (3 papers, 2008 to 2012). "The multistep process of intestinal-type carcinogenesis was also supported by the detection of an increased of mRNA expression and MYC copy number during the sequential steps, which begins with atrophic gastritis and is followed by intestinal metaplasia and carcinoma." (PMID 21811552, 2011). "FISH assay and CNV analysis by qRT-PCR showed that normal mucosa, non-atrophic gastritis, and atrophic gastritis samples of MNU-treated C. apellas presented mainly cells with 2 MYC copies." (PMID 21811552, 2011). "Although negative MYC immunoreactivity was observed, the mRNA expression was about 2-fold higher on 120th day (atrophic gastritis) compared to baseline." (PMID 21811552, 2011).
bone metastasis (3 papers, 2021 to 2025). Transfer of a neoplasm from its primary site to bones. "For OS, we considered sex, smoking history, bone metastasis, liver metastasis, CTNNB1 mutation, and MYC amplification." (PMID 41221800, 2025). "Based on univariate analysis results, the 3 genes (EGFR, HER2, MYC) and the 3 clinicopathological features (age, The Eastern Cooperative Oncology Group, and bone metastasis) were included in multivariate analysis." (PMID 34477158, 2021). "The results showed that 3 clinicopathologic factors (age, The Eastern Cooperative Oncology Group, and bone metastasis) and 3 genes (EGFR, HER2, MYC) have significant correlation with PFS." (PMID 34477158, 2021).
bone tumor (3 papers, 2022 to 2025). "Amplification of MET and MYC genes were negatively correlated with clinical prognosis in bone tumors (p<0.01)." (PMID 37546405, 2023).
cerebral infarction (3 papers, 2021 to 2023). An ischemic condition of the brain, producing a persistent focal neurological deficit in the area of distribution of the cerebral arteries. "Another previous study indicated that downregulated miR-200a could protect neural stem cells from cerebral infarction injury, possibly by regulating the STAT and MAPK/c-MYC signaling pathways." (PMID 34976005, 2021).
choroid plexus papilloma (3 papers, 2018 to 2019). "The tumorigenic consequences of persistent MYC expression of this model emerged later in adult mice as choroid plexus carcinoma and ciliary body medulloepithelioma, exposing the select vulnerability of certain subtypes of epithelial cells in the Nestin lineage to tumorigenesis." (PMID 29745900, 2018).
CNS DLBCL (3 papers, 2014 to 2021). "Thus, it remains unclear whether certain MYC mutations could contribute to increased MYC protein expression in CNS DLBCL." (PMID 25479599, 2014). "The CNS DLBCL-specific miR-26a downregulation that we present here is also in line with the previous studies suggesting an MYC-miR-26a-EZH2 positive feedback loop in aggressive B-NHLs." (PMID 34572608, 2021). "The reported frequencies of MYC rearrangement in CNS DLBCL (3–8% in prior studies and 9% in our study) are slightly lower than those reported in systemic DLBCL (10–15%)." (PMID 25479599, 2014). "Activation of the NF-κB pathway, either directly or indirectly via activation of the B-cell receptor pathway, could represent an alternative mechanism of MYC deregulation in CNS DLBCL, since NF-κB is a known transcriptional activator of MYC." (PMID 25479599, 2014). "Exonic, hot spot mutations associated with MYC deregulation have not been reported in CNS DLBCL." (PMID 25479599, 2014). "The incidence of MYC rearrangements has been reported to be slightly lower in CNS DLBCL (3–8%), and limited data thus far have not shown any prognostic impact of these rearrangements." (PMID 25479599, 2014). "In contrast, MYC rearrangements have not thus far been shown to be prognostically relevant in CNS DLBCL." (PMID 25479599, 2014). "However, a microRNA mediated pathway of MYC overexpression has not yet been described in CNS DLBCL." (PMID 25479599, 2014).
embryonal carcinoma (3 papers, 2021 to 2023). A non-seminomatous malignant germ cell tumor characterized by the presence of large germ cells with abundant cytoplasm resembling epithelial cells, geographic necrosis, high mitotic activity, and pseudoglandular and pseudopapillary structures formation. "Single-cell RNAseq studies on NANOS2 deficient germ cells (collected on D15.5) and embryonal carcinoma cells showed that both develop a transcriptional profile enriched for MYC and NODAL signaling and primed pluripotency." (PMID 35676718, 2022).
endometrial tumors (3 papers, 2010 to 2023). "We further identified the presence of genomic amplifications in SOX2 and MYC in endometrial tumors, and we observed the association of SOX2 and MYC amplifications with poor differentiation status." (PMID 30510261, 2018). "A correlation analysis showed that both SOX2 and MYC amplifications were significantly associated with advanced grade in endometrial tumors." (PMID 30510261, 2018). "Thus, in this study, we checked the association of SOX2, OCT4, NANOG, and MYC expressions with histological differentiation of endometrial tumors, and observed that the expressions of SOX2 and MYC, but not that of OCT4 and NANOG, correlate with advanced tumor grades." (PMID 30510261, 2018). "In this study, we observed that the expression of SOX2 and MYC, but not that of OCT4 and NANOG, in endometrial tumors is associated with poor histological differentiation and prognosis, suggesting the involvement of SOX2 in oncogenesis." (PMID 30510261, 2018).
esophageal tumors (3 papers, 2020 to 2024). "Current research on MYC shows that its oncoprotein is abnormally expressed in oral and esophageal tumors, and its amplification is closely related to the occurrence and development of esophageal tumors." (PMID 34568328, 2021).
Familial adenomatous polyposis (3 papers, 2012 to 2020). Familial adenomatous polyposis (FAP) is characterized by the development of hundreds to thousands of adenomas in the rectum and colon during the second decade of life. "Oncogenic activation of c-MYC can also occur through events upstream of c-MYC leading to uncontrolled c-MYC expression as observed for example in familial adenomatous polyposis and in K-RAS induced pulmonary carcinoma.." (PMID 24130880, 2013).
Fanconi anemia (3 papers, 2018 to 2025). Fanconi anemia (FA) is a hereditary DNA repair disorder characterized by progressive pancytopenia with bone marrow failure, variable congenital malformations and predisposition to develop hematological or solid tumors. "In contrast, KBM7 cells displayed a dependency on several genes associated with the Fanconi anemia pathway, but not for either of the Yamanaka factors except for the core essential gene MYC." (PMID 33228647, 2020).